SNORA17B (small nucleolar RNA, H/ACA box 17B )
Synonyms: ACA43; SNORA43
Gene: Small nucleolar RNA gene on chromosome 9 (136,726,104 to 136,726,239, reverse strand). Ensembl gene ENSG00000280496.
Gene Ontology:
Biological process: RNA processing
Cellular component: nucleolus
Homologues: Orthologues: chimpanzee SNORA17B (100% identical), macaque SNORA17B (94% identical). Paralogues in human: SNORA17A (57% identical).